RB1 (RB transcriptional corepressor 1)
Diseases named in the same sentence as RB1 in open-access papers (continued):
Sharing a sentence is not in itself a finding about the gene and the disease.
retinoblastoma (continued). "We have developed iPSCs from 15 participants with germline RB1 alterations and we have optimized a 3D retinal organoid culture system for producing human retinoblastoma in the laboratory." (PMID 34315877, 2021). "This suggests that undetected RB1 mutations possibly involving translocations, intronic mutations or novel promoter mutations may be harboured by these tumours, or the development of some retinoblastoma tumours may be driven through an RB1-independent mechanism." (PMID 33670346, 2021). "Familial and/or bilateral retinoblastomas most often develop in children harboring germline RB1 deletions, only after the occurrence of a “second hit”, corresponding to the loss of the second RB1 allele." (PMID 33802620, 2021). "BCOR and CREBBP should be included, along with RB1, in any future targeted sequencing in order to maximise the capture of recurrent non-RB1 genetic variations within retinoblastoma patients." (PMID 33805427, 2021). "In all families with retinoblastoma history, we identified molecular genetic alterations of the RB1 gene either by DNA sequencing or by multiplex ligation-dependent probe amplification (MLPA)." (PMID 34680218, 2021). "Retinoblastoma is thought to follow a multistep model for tumor progression and bi-allelic inactivation of the RB1 gene alone, though sufficient for retinoblastoma genesis, seems not sufficient for tumor progression, since all our patients show additional CNA." (PMID 33567541, 2021). "A small minority of retinoblastoma cases (<1%) have been found to have two active copies of the RB1 gene but somatic MYCN amplification." (PMID 33805427, 2021). "Retinoblastoma is a rare, intraocular cancer that arises in the developing retina, primarily due to bi-allelic inactivation of the RB1 gene." (PMID 32770435, 2020). "Retinoblastoma (OMIM #180200), representing the most frequent ocular cancer of the pediatric age, is caused by biallelic inactivation of RB1 tumor suppressor gene." (PMID 32224912, 2020). "RB1 gene is a tumor suppressor gene whose inactivation is responsible for one of the important childhood malignancies, retinoblastoma (Rb)." (PMID 35006436, 2020). "Nevertheless, homozygous knockout of RB1 has been conducted in ESCs to model and study the genesis of trilateral retinoblastoma via teratoma formation." (PMID 32824373, 2020). "Loss of HELLS drastically reduced ectopic division of differentiating cells in Rb1/p107-null retinae, significantly decreased the incidence of retinoblastoma, delayed tumor progression, and increased overall survival." (PMID 32071286, 2020). "Rb1+/− mice were initially developed to model retinoblastoma, but instead of retinoblastomas these mice developed a large variety of NETs31,49." (PMID 32198354, 2020). "Retinoblastoma is a rare eye cancer that occurs in one or both eyes of infants and young children as a result of errors in the RB1 gene." (PMID 32161663, 2020). "Although it is well known that methylation of the RB1 promoter is a rather frequent inactivating event in retinoblastoma cancer cells, the role of constitutive epimutations has been poorly investigated and it has long been controversial." (PMID 32224912, 2020). "This is known as RB1 gene deletion syndrome and apart from retinoblastoma it is characterised by dysmorphia and developmental delay." (PMID 32047660, 2020). "Despite the seemingly dispensable role of Hells in retinal development, we found that persistent expression of Hells in Rb1/p107-null retinal cells is critical for ectopic proliferation and retinoblastoma tumor progression." (PMID 32071286, 2020). "The decrease in tumor burden and morbidity observed in Rb1/p107/Hells TKO mice presents HELLS as an attractive potential therapeutic target for the treatment of retinoblastoma." (PMID 32071286, 2020).
retinoblastoma (continued). "Alteration of the cyclin-dependent kinase 4–6 (CDK4-6) pathway is common in several types of cancers, including GBM; a phase II trial evaluated palbociclib, an oral inhibitor of CDK4–6, in rGBM patients with RB1 (Retinoblastoma) proficiency in IHC." (PMID 33375286, 2020). "While genetic alterations in the RB1 gene are required for tumor initiation, retinoblastoma tumors have stable genomes, with tumor progression occurring through epigenetic dysregulation of several cancer pathways." (PMID 32071286, 2020). "Inactivation of the retinoblastoma tumor suppressor gene (RB1) leads to genome instability, and can be detected in retinoblastoma and other cancers." (PMID 33271982, 2020). "The majority of retinoblastoma cases are initiated by the biallelic inactivation of the RB1 gene (RB1−/−)." (PMID 32971811, 2020). "Retinoblastoma is an aggressive childhood cancer of the developing retina that initiates by biallelic RB1 gene inactivation." (PMID 32071286, 2020). "We describe a patient with retinoblastoma in which we detected a novel RB1 c.2548C > T, p.(Gln850Ter) and a synchronous MET c.3029C > T, p.(Thr1010Ile) mutation as well." (PMID 33375764, 2020). "CBFB and ZNF384 are cancer genes for leukemia; RB1 is a gene for retinoblastoma, sarcoma and small-cell lung cancers and MAP3K4 is a gene for pancreatic, breast and colorectal cancers, as listed on the Cancer Gene Census." (PMID 33087126, 2020). "They concluded that retinoblastoma tumorigenesis requires somatic inactivation of the retinoblastoma RB1 locus near the esterase D locus." (PMID 31683923, 2019). "In this analysis, we sought to understand how the homozygous deletion of the RB1 gene changed the transcriptional profile of both coding and non-coding genes in the rare pediatric tumor, Retinoblastoma." (PMID 31058073, 2019). "Inhibition of Nodal using multiple short hairpin (shRNAs) in WERI Rb1 and Y79 retinoblastoma cell cultures reduced growth by more than 90%, as determined by CCK-8 growth assay." (PMID 31451106, 2019). "Since its discovery, the stepwise characterization and cloning of RB1 have laid the foundation for numerous advances in the understanding of tumor suppressor genes, retinoblastoma tumorigenesis, and inheritance." (PMID 31683923, 2019). "Retinoblastoma and the RB1 tumor suppressor gene led to a paradigm shift in cancer genetics in the late 1980s and early 1990s, with increased acceptance and understanding of the concept and molecular function of tumor suppressor genes." (PMID 31683923, 2019). "Our understanding of retinoblastoma tumorigenesis and heritability has dramatically broadened as a result of the study and cloning of the RB1 gene." (PMID 31683923, 2019). "This article reviews the long history of RB1 gene research, characterization, and cloning, and also discusses recent advances in retinoblastoma genetics that have grown out of this foundational work." (PMID 31683923, 2019). "To determine how the loss of the Retinoblastoma 1 (RB1) tumor-suppressor gene changes the expression of coding and non-coding RNAs in tumors, we conducted RNA-sequencing (RNA-seq) from 7 Retinoblastoma patients." (PMID 31058073, 2019). "This analysis confirmed that E2F target genes are consistently increased in RB1-mutant Retinoblastomas." (PMID 31058073, 2019). "The RB1 gene is the first described human tumor suppressor gene and plays an integral role in the development of retinoblastoma, a pediatric malignancy of the eye." (PMID 31683923, 2019). "The esterase D gene was subsequently cloned and shown to be normal in most retinoblastoma tumors, demonstrating that it was separate from the RB1 locus." (PMID 31683923, 2019). "A number of leading laboratories around the globe have used microarray technology to determine the transcriptional changes in RB1-/- Retinoblastoma samples compared to normal retinal controls." (PMID 29868118, 2018).
retinoblastoma (continued). "Similar apoptotic responses upon UHRF1 knockdown were observed for another retinoblastoma cell line, Weri-Rb1." (PMID 29415984, 2018). "The XRCC4 downregulation upon UHRF1 knockdown was observed in other retinoblastoma cell lines (Weri-Rb1 and SO-Rb50) and 293T cells, and occurred at the transcript level." (PMID 29415984, 2018). "Homozygote inactivation of the Rb1 gene is the initial event triggering the development of Retinoblastoma." (PMID 29868118, 2018). "A second model by the same group used CRISPR/Cas9-mediated knockout of rb1 and rbl1 genes in Xenopus tropicalis to phenocopy Retinoblastoma, a paediatric tumour of the developing retina." (PMID 30538639, 2018). "Inactivation of rb1 is thought to promote either induction or progression events in a variety of cancers such as retinoblastoma, prostate cancer, small cell lung cancer, etc.." (PMID 28903419, 2017). "Retinoblastoma is an intraocular tumor which arises from developing retina by RB1 gene inactivation." (PMID 28467809, 2017). "In this manuscript, we investigated the characteristics of MYCN‐amplified sporadic unilateral retinoblastoma and the mechanisms of inactivation of the RB1 gene in these tumors." (PMID 28211617, 2017). "RB1 contributes to regulating epigenetic processes such as DNA methylation and histone modification; thus, RB1 inactivation leads to retinoblastoma." (PMID 28420213, 2017). "RB is an extensively studied cancer of the developing retina, and the distinctive clinical features of bilateral tumors and a younger age at diagnosis is associated with the presence of germline mutations in the tumor suppressor retinoblastoma 1 (RB1) gene." (PMID 28193182, 2017). "We previously developed a murine model of retinoblastoma that deleted RB1 and p107 to unleash E2F-driven proliferation and apoptosis, and co-deleted Pten to suppress apoptosis and form bilateral retinoblastoma tumors." (PMID 28445155, 2017). "Retinoblastoma (RB) is a retinal cancer associated with biallelic loss of RB1 gene." (PMID 28575107, 2017). "We applied our approach to 268 newly identified de novo germline mutations by re-sequencing the coding exons and flanking intronic regions of RB1 in 642 sporadic, bilateral probands affected with retinoblastoma (RB)." (PMID 28193182, 2017). "Whilst the level of H3K4me3 modification of telomeric histone was unaffected by retinoblastoma status (p = 0.5016), the representation of both H3K9me3 and H3K9ac in the telomeric chromatin was significantly increased in haploinsufficient (Rb1+/Δ19) cells." (PMID 28169375, 2017). "13.3% of the cases studied (affected eyes) were classified as hereditary/genetic, 86.7% fall in the category of sporadic retinoblastoma confirmed by fluorescent in situ hybridisation for the RB1 gene." (PMID 28798812, 2017). "In mice, MYCN overexpression alone was insufficient to drive retinoblastoma development, however, tumors formed when overexpression was combined with RB1 deletion." (PMID 29124525, 2017). "The reported incidence of OS is significantly higher in patients with retinoblastoma, which suggests the role of the RB1 gene in tumorigenesis of both diseases." (PMID 29244987, 2017). "In another recent publication three retinoblastoma subtypes were compared in human tumors based on RB1 and MYCN; RB1−/−MYCNA, RB1+/−MYCNA, and RB1+/+MYCNA." (PMID 29124525, 2017). "Retinoblastoma develops as a result of inactivation of the tumor suppressor RB1 gene, 40% of RBs are heritable tumors and 60% are non heritable tumors." (PMID 29261756, 2017). "We analyzed the mutation status of the RB1 gene and MYCN copy number in a series of 245 unilateral retinoblastomas, and the phosphorylation status of pRb in a subset of five tumors using immunohistochemistry." (PMID 28211617, 2017). "We previously showed that Rb1 loss cooperates with either co-activating the phosphatidylinositol 3-kinase (PI3K)/AKT pathway, or co-deleting Pten, to initiate retinoblastoma tumors in mice." (PMID 28445155, 2017).
retinoblastoma (continued). "MCC, however, seems to belong to a group of tumors, like small cell lung cancer and retinoblastoma in which inactivation of only RB1 is sufficient to allow tumor formation." (PMID 27121059, 2016). "Different mouse models are available, all based on genetic deactivation of both Rb1 and Retinoblastoma-like 1 (Rbl1), and each showing different kinetics of retinoblastoma development." (PMID 27739525, 2016). "By extension, this strongly suggests that modeling retinoblastoma by knocking out Rb1 and Rbl1 in mice is a suitable approach, which we expect to be similar in other animals models, such as Xenopus tropicalis." (PMID 27739525, 2016). "Here, we show by CRISPR/Cas9 techniques that similar to the mouse, neither rb1 nor rbl1 single mosaic mutant Xenopus tropicalis develop tumors, whereas rb1/rbl1 double mosaic mutant tadpoles rapidly develop retinoblastoma." (PMID 27739525, 2016). "Our analyses of enucleated retinoblastoma showed that SNVs/INDELs beyond RB1 inactivation were extremely rare." (PMID 27126562, 2016). "We next analyzed expression levels of Notch pathway components in WERI Rb1 and Y79 retinoblastoma cell lines." (PMID 27661116, 2016). "Down-regulation of RB1 is involved in various types of cancers, including osteosarcoma, Retinoblastoma and lung adenocarcinoma." (PMID 27036041, 2016). "Retinoblastoma is a pediatric eye tumor in which bi-allelic inactivation of the Retinoblastoma 1 (RB1) gene is the initiating genetic lesion." (PMID 27739525, 2016). "The retinoblastoma was strongly enriched in two rb1 frameshift deletions (85%; Δ52 and Δ7) and an rbl1 insertion (58%; +36)." (PMID 27739525, 2016). "Retinoblastoma development is initiated by two sequential hits of RB1 (RB1-/- patients) and in few cases by amplification of MYCN (RB1+/+MYCNA patients)." (PMID 27115612, 2016). "The first report by Greger in 1989 on the silencing by methylation of the RB1 promoter in retinoblastomas noted the importance of the methylation silencing of the promoter of a tumor suppressor gene in oncogenesis." (PMID 26753011, 2016). "For example, mutations in RB1 stabilize the 5′‐UTR secondary structures and are likely conducive to retinoblastoma." (PMID 26992833, 2016). "The RB1 gene is named after the corresponding cancer type hereditary retinoblastoma, where the gene is homozygously deleted." (PMID 26576131, 2015). "Retinoblastoma, the most common childhood intraocular tumor has complex genetic basis of cancer development, initiated by biallelic inactivation of RB1 gene." (PMID 25928201, 2015). "The essential role for Rb1 in the retina, a tissue of neuroectodermal origin, is documented by the development of retinoblastoma upon biallelic inactivation of RB1 in humans." (PMID 26275142, 2015). "Most retinoblastomas initiate from a bi-allelic loss of the RB1 gene, which encodes a critical regulator (pRb) of the cell cycle." (PMID 26379276, 2015). "While the molecular etiology of the retinoblastoma eye tumor is one of the simplest among all human cancers, the significance of RB1 functional complexity and interactions, as well as its relevance in normal development and malignancies, is a work in progress." (PMID 25755634, 2015). "In striking contrast, co-deleting Pten with Rb1 and p107 in RPCs induced rapid bilateral retinoblastoma formation." (PMID 25907958, 2015). "To determine if there was any difference in the molecular features of this retinoblastoma with wild type RB1 and MYCN amplification, we performed gene expression array analysis." (PMID 24509483, 2014). "It has been previously reported that a small proportion (1.5%) of retinoblastomas with MYCN amplification express wild type RB1." (PMID 24509483, 2014).
retinoblastoma (continued). "This provides a novel mechanism of retinoblastoma initiation and suggests that molecular assays to detect RB1 chromothripsis should be included in future analyses of this important tumor suppressor pathway." (PMID 24509483, 2014). "Whole genome sequencing combined with break-apart FISH analysis of the RB1 locus and RB1 IHC can be used to identify this unique subset of retinoblastoma tumors." (PMID 24509483, 2014). "To explore the differential cytotoxicity of THPTS-PDT on non-degenerated retinal cell populations, we compared the phototoxic effect in retinoblastoma (WERI Rb-1) and normal primary human retinal pigmented epithelium cells (hRPE)." (PMID 24498108, 2014). "To characterize the relationship between MYCN amplification and RB1 gene inactivation, we analyzed the RB1 gene status in 46 retinoblastomas with sufficient DNA for custom capture Illumina sequencing." (PMID 24509483, 2014). "Almost all retinoblastomas have RB1 gene inactivation and RB1 gene inactivation is sufficient to promote retinoblastoma." (PMID 25338120, 2014). "Over the past 27 years since the RB1 gene was cloned, researchers have focused on identifying genetic lesions in retinoblastoma that contribute to tumor progression following RB1 inactivation." (PMID 24509483, 2014). "Limited understanding of the Rb1 locus hinders genetic and epigenetic analyses of Retinoblastoma, a childhood cancer of the nervous systems." (PMID 24478791, 2014). "Taken together, our data suggest that MYCN and OTX2 are the most common focal gains found in retinoblastoma and RB1, and BCOR are the most common focal losses found in retinoblastoma." (PMID 24509483, 2014). "Retinoblastoma is a relatively simple tumor that initiates with a common genetic lesion (RB1 inactivation) and progresses rapidly in children." (PMID 23765217, 2013). "In conclusion, MLPA is a strong method for primary evaluation of RB1 gene deletions/duplications in patients with retinoblastoma." (PMID 23441118, 2013). "Retinoblastoma is a childhood cancer of the developing retina that initiates with biallelic inactivation of the RB1 gene." (PMID 23765217, 2013). "Several different mechanisms have been proposed to explain the rapid progression of retinoblastoma following RB1 inactivation." (PMID 23765217, 2013). "Overall, these data are consistent with previously published data on human retinoblastomas and RB1-depleted human RPE cells showing that loss of RB1 leads to defects in sister chromatid cohesion." (PMID 23765217, 2013). "In this study, we analyzed the species-specific role of RB1 in maintaining genome stability and the epigenetic landscape in the developing retina as it relates to retinoblastoma tumor initiation and progression." (PMID 23765217, 2013). "Accordingly, in the present study, the detection rate of RB1 gene gross rearrangements in a large cohort of Iranian patients with retinoblastoma was investigated with MLPA." (PMID 23441118, 2013). "The RB1 and BCOR (13%) genes are the only genes found to be recurrently mutated in human retinoblastomas to date." (PMID 23765217, 2013). "An abnormal retinoblastoma susceptibility gene (RB1) is the main cause of the occurrence of RB." (PMID 23109819, 2012). "High ARF mRNA but low ARF protein also suggests attenuation of synthesis or instability of ARF in most RB1-/- retinoblastoma cell lines." (PMID 22336108, 2012). "Approximately 40% of retinoblastoma patients carrying a germline mutant of RB1 have a bilateral retinoblastoma tumor, and these patients are more likely to develop secondary tumors." (PMID 22876131, 2012). "In contrast, miR-21 expression was significantly lower in rapidly dividing, non-endothelial cell lines; immortalized kidney (HEK293T) and retinoblastoma (Weri-Rb1)." (PMID 22298343, 2012). "Our miR-24 and ARF protein expression data are in agreement with ARF protein regulation by miR-24 that is unique to RB1-/- retinoblastomas." (PMID 22336108, 2012).